EDAR (ectodysplasin A receptor)
Diseases named in the same sentence as EDAR in open-access papers (continued):
Sharing a sentence is not in itself a finding about the gene and the disease.
otitis media (1 paper, 2019). Inflammation of the anatomical structures of the middle ear, which is most often caused by an infectious process. "This makes it likely that hypomorphic as well as null mutations in EDAR signalling pathway genes in humans will impact on gland structure and function, and predispose individuals to otitis media." (PMID 31028034, 2019). "In conclusion, we report that the agonist anti-EDAR antibody rescues auditory-tube glands in EdaTa mice and prevents rhinitis and otitis media." (PMID 31028034, 2019).
rhinitis (1 paper, 2019). An inflammation of the mucous membrane lining the nose, usually associated with nasal discharge. "Agonist anti-EDAR antibody treatment reduces rhinitis more than hyaline droplet accumulation, suggesting that other factors may work in concert with nasal inflammation to cause this cellular change." (PMID 31028034, 2019).
tumor (7 papers, 2018 to 2025). "We also examined EDAR expression in tumor tissues from recurrent (n = 5) and non‐recurrent (n = 5) patients with NPC using IHC." (PMID 40995667, 2025). "Tumour tissue displayed elevated EDAR target gene expression and an increase in nuclear p65, indicative of ongoing increased NFκB signalling." (PMID 34916592, 2022). "Within this dataset, there was a small group of tumours that expressed very high levels of EDAR, which almost invariably belonged to the basal-like subgroup." (PMID 34916592, 2022). "This β-catenin activity is required for tumour cell proliferation, highlighting the interplay between EDAR and WNT pathways in tumourigenesis." (PMID 34916592, 2022). "Immunofluorescence confirmed the expression of EDAR in human cluster cells and its absence in the glial reactive tissue, further confirming similarities between ACP clusters and the enamel knot (n = 5 human tumours)." (PMID 29541918, 2018). "Additionally, both EDAR knockdown and NFκB inhibitor pretreatment weakened T cell cytotoxicity against NPC cells, reduced the number of T cells recruited by tumor cell supernatants, and decreased the proportion of GZMB+CD8+ T cells in the supernatant‐treated T cell population." (PMID 40995667, 2025).
cancer (5 papers, 2011 to 2024). A tumor composed of atypical neoplastic, often pleomorphic cells that invade other tissues. "This review highlights the roles of EDA signaling in different physiological and pathological processes, and discusses the clinical application of Fc-EDA protein in HED and the possible drug development of EDAR inhibitors for cancer treatment." (PMID 36012178, 2022). "EDA signaling mainly regulates skin appendage development, but emerging evidence suggests that the receptor EDAR, solely in the absence of EDA, may have unexpected functions involved in tumorigenesis and cancer progression." (PMID 36012178, 2022).
EDAR also shares sentences with these, for which no sentence is quoted: genetic disorder (3 papers); X-linked hypohidrotic ectodermal dysplasia (3); acne (1); Alopecia universalis (1); amyloidosis (1); Andermann syndrome (1); asthma (1); Ataxia (1); beta thalassemia (1); bleeding disorder (1); cardiovascular disease (1); Carvajal syndrome (1); cleft lip (1); cutaneous melanoma (1); dementia (1); factor XI deficiency (1); Hypodontia (1); hypotrichosis 4 (1); hypotrichosis 6 (1); infectious mononucleosis (1); Intellectual disability (1); metabolic syndrome (1); nasopharyngeal carcinoma (1); Netherton syndrome (1); odonto-onycho-dermal dysplasia and (1); psoriasis (1); pure hair and nail ectodermal dysplasia (1); rheumatoid arthritis (1); Schöpf-Schulz-Passarge syndrome (1); vitamin D deficiency (1).